METTL14 (methyltransferase 14, N6-adenosine-methyltransferase non-catalytic subunit)
Diseases named in the same sentence as METTL14 in open-access papers (continued):
Sharing a sentence is not in itself a finding about the gene and the disease.
lung carcinoma (continued). "In vitro assays suggested that METTL14 knockdown suppressed lung cancer progression." (PMID 38725005, 2024). "Some research found that ALKBH5 knockout resulted in spermatogenesis defects due to elevated spermatocyte apoptosis; disruption of the transcription process by METTL3 and METTL14 could lead to lung fibrosis and lung cancer metastasis." (PMID 38133427, 2023). "Furthermore, in vivo assays revealed that METTL14 knockdown suppressed lung cancer progression." (PMID 38725005, 2024). "The study found that METTL3 and METTL14 interact with chromatin and the transcriptional machinery, suggesting that disruption of this process could lead to the development of diseases, such as lung fibrosis and lung cancer metastasis." (PMID 38133427, 2023). "Co-expression analysis in lung cancer tissues also confirmed that GPX2 was positively correlated with Hedgehog signaling and cancer stem cell markers while negatively correlated with METTL14." (PMID 40533443, 2025). "METTL14, METTL16, METTL7B and IGF2BP3 jointly and positively mediate GPX4 mRNA stability and protein levels, suppressing ferroptosis in lung carcinoma, breast cancer and osteoclasts." (PMID 41373022, 2025). "The METTL14-YTHDF2 axis enhances KCTD10 mRNA stability via m6A modification, clarifying the regulatory mechanisms of low KCTD10 expression in lung cancer." (PMID 40873559, 2025). "The disruption of METTL14 contributed to CD8+T-cell activation and the immunotherapy response to PD-1 via m6A modification of HSD17B6, thereby suppressing lung cancer progression." (PMID 38725005, 2024). "Here, the disruption of METTL14 contributed to CD8+T-cell activation and the immunotherapy response to PD-1, thereby suppressing lung cancer progression." (PMID 38725005, 2024). "Here, we unveiled METTL14/IGF2BP2-mediated m6A modification of AC026356.1, which lead to its high expression in lung cancer." (PMID 37142269, 2023). "The results showed that the expression profiles of eight m6A regulators (ALKBH5, FTO, HNRNPC, METTL14, RBM15, YTHDC1, YTHDC2, and ZC3H13) were significantly different among the three different lung cancer subtypes (P < 0.01)." (PMID 34805165, 2021). "To investigate how m6A is regulated in KL lung cancer, we compared the expression of proteins that act as the m6A writer complex (METTL3, METTL14, and WTAP) and erasers (ALKBH5 and FTO)." (PMID 34016959, 2021). "We also tested the expression of m6A writers METTL3, METTL14, and WTAP and of erasers ALKBH5 and FTO after the treatment of IL-37 in A549 cells and lung cancer tissues." (PMID 33489865, 2020). "We also showed the expression of m6A writers METTL3, METTL14, and WTAP and erasers ALKBH5 and FTO in A549 cells and lung cancer tissues after the treatment of IL-37." (PMID 33489865, 2020). "Both METTL14 and YTHDF2 exhibit low expression in lung cancer but are positively correlated with better patient prognosis, suggesting that impaired METTLE14-YTHDF2 activity contributes to the downregulation of KCTD10 in lung cancer." (PMID 40873559, 2025). "M6A-modified METTL14/IGF2BP2/AC026356.1 loop may serve as a potential therapeutic target and prognostic predictor for lung cancer therapy and diagnosis in the clinic." (PMID 37142269, 2023). "Functional analysis corroborated that AC026356.1 acted as a downstream target of METTL14/IGF2BP2 and AC026356.1 silencing could block the oncogenicity of lung cancer stem-like cells." (PMID 37142269, 2023). "The expression of METTL14 is reduced in lung cancer tissues, and its function in lung cancer has not been clearly studied." (PMID 34476213, 2021).
melanoma (23 papers, 2019 to 2026). A malignant, usually aggressive tumor composed of atypical, neoplastic melanocytes. "Nonetheless, METTL3 and METTL14 are risk genes in melanoma based on published research, while the results of this study indicated WTAP as a protective factor." (PMID 41301778, 2025). "On the contrary, multiple reports have indicated that METTL3 and METTL14 were risky and drug-resistant genes associated with melanoma." (PMID 41301778, 2025). "Depletion of Mettl3 and Mettl14 significantly upregulated PD-L1, and Mettl3 or Mettl14 deficient enhanced the response to anti-PD-1 treatment in pMMR-MSI-L CRC and melanoma." (PMID 36960074, 2023). "Then, we analyzed the somatic mutations of 21 m6A regulators in TCGA melanoma; 19 m6A regulators displayed mutations, with the exception of only two genes (METTL14 and ALKBH5) in melanoma tissues." (PMID 34900983, 2021). "Similarly, the deletion of METTL3 or METTL14 in immune-resistant melanoma tumor cells makes the tumor sensitive to immunotherapy." (PMID 39372415, 2024). "We discovered that N6-methyladenosine (m6A) modulators-specifically YTHDF3, YTHDC1, and METTL14-cooperatively upregulate BGN expression in a parallel, non-hierarchical manner converging on functional m6A sites within melanoma cells." (PMID 41833003, 2026). "Depletion of the methyltransferase METTL3 and METTL14 to suppress m6A mRNA modification enhanced the response of pMMR-MSI-L CRC and melanoma to anti-PD-1 therapy." (PMID 41194259, 2025). "We then investigated the expression of common methyltransferases and demethylases like METTL3, METTL14, FTO and ALKBH5 in three melanoma cell lines, which demonstrated that the process of m6A modification was available in melanoma cell lines." (PMID 36324258, 2022). "For instance, expression of METTL3 in macrophages was suggested to synergize with PD-1-based therapy in B16 melanoma, and METTL3 and METTL14 have been shown to regulate immune response to anti-PD-1 treatment in melanoma and colorectal carcinoma." (PMID 35558067, 2022). "Inhibition of m6A mRNA modification by depletion of methyltransferases, Mettl3 and Mettl14, enhanced response to anti-PD-1 treatment in pMMR-MSI-L CRC and melanoma." (PMID 34526985, 2021). "Intriguingly, both “writers” inhibition (METTL3 or METTL14) and “erasers” inhibition (FTO or ALKBH5) are proved to enhance the efficacy of anti-PD-1 blockade even in the same cancer (melanoma)." (PMID 34526985, 2021). "To determine the role of m6A in melanoma cell function, we performed gain-of-function tests of the m6A writers METTL3 (Methyltransferase Like 3) and METTL14 (Methyltransferase Like 14)." (PMID 31239444, 2019). "In melanoma, this context-specific regulation may explain why WTAP displays tumor-suppressive properties, in contrast to the oncogenic roles of METTL3 and METTL14." (PMID 41301778, 2025). "Moreover, depletion of Mettl3 and Mettl14 enhanced the response to anti-PD-1 treatment in pMMR-MSI-L CRC and melanoma." (PMID 34526985, 2021). "To determine whether regulation of these melanoma-promoting genes by FTO is m6A-dependent, we assessed the role of m6A by knocking down the m6A methyltransferases METTL3 and METTL14." (PMID 31239444, 2019). "Furthermore, knockdown of METTL3 and METTL14 prevented the effect of FTO knockdown on cell growth/proliferation, migration, invasion, and cell viability in melanoma cells in suspension." (PMID 31239444, 2019). "The inhibition of METTL3 and METTL14 via methyltransferase inhibitors suppressed N-methyladenosine (mA) mRNA modification and enhanced the response to anti-PD-1 therapy in pMMR-MSI-L CRC and melanoma, highlighting the relevance of RNA methylation in adaptive immunity." (PMID 34230220, 2021).
melanoma (continued). "Ultimately, however, they suggest that the regulation of these melanoma-promoting genes by FTO and other proteins might critically affect gene expression in melanoma (e.g., the methyltransferases METTL3 and METTL14) and further studies on the therapeutic potential of such are warranted." (PMID 34105069, 2021).
cervical carcinoma (21 papers, 2017 to 2025). A carcinoma arising from either the exocervical squamous epithelium or the endocervical glandular epithelium. "The upregulation of METTL14 mRNA expression is significantly associated with improved OS in patients with cervical cancer." (PMID 37915034, 2023). "For example, in cervical cancer, the TRIM11 mRNA’s stability is enhanced by IGF2BP1 depending on m6A modification, which is mediated by METTL14 and accelerates cervical cancer progression by mediating PHLPP ubiquitination." (PMID 39557826, 2024). "piR-14633 was observed to promote proliferation, migration, and invasion of cervical cancer cells by METTL14/CYP1B1 signaling axis." (PMID 38182573, 2024). "piRNA‐14633 stimulates the expression of CYP1B1 through METTL14‐mediated m6A methylation, thereby enhancing the proliferation, migration, and invasion capabilities of cervical cancer cells." (PMID 39660878, 2024). "It has been shown that piRNA accumulation has concentration-dependent effects on the production of METTL14 in cervical carcinoma." (PMID 38125749, 2023). "PiRNA-14633 mimics elevated levels of m6A RNA methylation and stabilized METTL14 mRNA, which eventually aided in the formation of cervical cancers." (PMID 38125749, 2023). "Downregulation of METTL14 inhibits the migratory and invasive capabilities of cervical cancer cells in vitro." (PMID 37915034, 2023). "We also performed transwell assays and noticed that piRNA-14633 promoted the migration and invasion abilities of cervical carcinoma cells, while silencing of METTL14 impaired these phenotypes." (PMID 35093098, 2022). "To further study the relationship between piRNA-14633 and METTL14 in cervical carcinoma cells, we inhibited new mRNA synthesis of cervical carcinoma cells by a-Amanitin." (PMID 35093098, 2022). "Wound healing assays then showed that piRNA-14633 tended to increase migration of cervical carcinoma cells, which were reversed by si-METTL14#1 and si-METTL14#2." (PMID 35093098, 2022). "By RT-PCR, we found that piRNA-14633 overexpression increases half-life of METTL14 and piRNA-14633 knockdown decreases half-life of METTL14 in cervical carcinoma cells." (PMID 35093098, 2022). "Differential analysis results showed that many m6A-related genes were differentially expressed between cervical cancer tissues and normal tissues, including METTL14, METTL16, ZC3H13, YTHDC1, and YTHDC2." (PMID 36058934, 2022). "To further study the role of METTL14 in piRNA-14633-mediated cervical cancer cells, we knocked down METTL14 expression using small interference RNA (si-METTL14)." (PMID 35093098, 2022). "By Epiquik m6A RNA measurement quantifcation kit, we found that si-METTL14 decreased m6A methylation activity in cervical carcinoma cells." (PMID 35093098, 2022). "On the other hand, knocking-down adenosine demethylases (FTO and ALKBH5) or overexpressing adenosine methyltransferases (METTL3 and METTL14) suppressed cervical cancer development in vivo." (PMID 29228737, 2017). "Besides, piRNA‐14633 influences the malignancy of cervical cancer cells through the enhancement of m6A RNA methylation and the preservation of methyltransferase like 14 (METTL14) mRNA stability." (PMID 40737301, 2025). "However, METTL3 and METTL14 have also been found to be both anti-oncogenic factors in cervical cancer." (PMID 39967906, 2025). "This indicates that elevated levels of piRNA‐14633 may drive the growth, mobility, and invasiveness of cervical cancer cells through modulation of the METTL14/CYP1B1 signaling pathway." (PMID 40737301, 2025). "The expression of the METTL14 gene is decreased in cervical cancer." (PMID 37915034, 2023). "CCK-8 and colony formation assays showed that piRNA-14633 promoted the proliferation of cervical carcinoma cells and that si-METTL14 could block the promotion effect." (PMID 35093098, 2022).
cervical carcinoma (continued). "To verify whether piRNA-14633 targets METTL14 in cervical carcinoma cells, we predicted the binding site between piRNA-14633 and 3’UTR of METTL14 (mRNA 5'-3', 4364–4392) by bioinformatics software." (PMID 35093098, 2022). "Si-METTL14 could counteract the promoting effect of piRNA-14633 on the proliferation, migration and invasion of cervical cancer cells, suggesting that piRNA-14633 accelerates cervical cancer progression by inducing METTL14-mediated m6A methylation." (PMID 35093098, 2022). "In cervical cancer, a study suggested that the glycolytic process is targeted, programmed cell death protein 1 (PD-1) expression is facilitated, and macrophage phagocytic function is inhibited by high expression of the m6A regulator METTL14, which accelerates cancer progression." (PMID 39904996, 2025). "Specifically, we found lower expression of METTL3, METTL14, and WTAP transcripts, while RBM15 and ALKBH5 abundance was elevated in cervical cancer cells." (PMID 38665783, 2024). "METTL3, METTL14, and WTAP methylation levels in cervical cancer were reported to be considerably greater than in surrounding normal tissues in a prior investigation." (PMID 36091006, 2022). "METTL14, also an oncogene in cervical cancer, enhanced its m6A methylation levels by being mediated by piRNA-14633 (PIWI-interacting RNA-14633) to activate the piRNA-14633/METTL14/CYP1B1 axis which promoting the proliferation, invasion and metastasis of cervical cancer cells." (PMID 38343637, 2024). "We speculated that low expressed TRPV1 promotes cervical cancer tumorigenesis through YTHDF1/2/3, HNRNPA2B1, YTHDC1/2, ZC3H13, and METTL14 modification." (PMID 36072430, 2022). "Subsequent gene interaction network analysis indicated that 3 genes (ZC3H13, METTL14, and CBLL1) appeared to serve as network hubs, suggesting that dysregulation of m6A modification by these genes provided major contributions to the development and/or progression of cervical cancer." (PMID 35418160, 2022).
colitis (21 papers, 2020 to 2025). Inflammation of the colon. "Studies using CD4-Cre conditional knockout mice demonstrated that T cell–specific loss of Mettl14 leads to spontaneous colitis characterized by increased inflammatory infiltration, elevated colon weight/length ratio, and enhanced Th1/Th17 cytokine expression." (PMID 41164187, 2025). "Functional assays confirmed that Mettl14 loss compromises iTreg suppressive capacity both in vivo (colitis mouse models) and in vitro (CFSE inhibition assays)." (PMID 41164187, 2025). "In this study, we employed AOM and AOM/DSS‐induced intestinal epithelial cell (IEC)–specific METTL14 knockout (Mettl14ΔIEC) CRC mouse models to verify the crucial suppressive role of METTL14 in both adenoma and colitis‐associated malignant transformation." (PMID 36794620, 2023). "The loss in T cells of METTL14, a subunit of the RNA methyltransferase, induces spontaneous colitis in mice, according to a recent research." (PMID 35795532, 2022). "As an example, in mice, the deletion of an enzyme known as 14 (METTL14), which is part of the RNA methyltransferase complex, causes spontaneous colitis and a Th1/Th17 phenotype." (PMID 35795532, 2022). "Another study also indicated that METTL14 deficiency in T cells induces spontaneous colitis in mice due to dysfunctional Treg cells." (PMID 36341394, 2022). "Meanwhile, in line with our studies that specific deletion of Mettl14 in CD4+ T cells has also been shown to cause spontaneous colitis in mice, which is the outcome of T cell dysfunction and subsequent loss of the inhibitory activity of Treg cells." (PMID 36341394, 2022). "As a consequence, both the reduction of iTregs, whose function has reported to be controlling the experimental colitis, and the dysfunctional Mettl14 deficient Tregs lead to the development of spontaneous colitis." (PMID 34988083, 2021). "m6A has been reported its potential connections with IBD, METTL3 and METTL14 deficiency in immune cell induce colitis; m6A eraser FTO protects IBD patients from adverse reactions after thiopurine treatment." (PMID 35127705, 2021). "In our colitis model, the deletion of Mettl14 also leads to Treg dysfunction with loss of suppressive capacity." (PMID 32634481, 2020). "In summary, we have identified a new spontaneous colitis model mediated by T cell deficiency of METTL14, a component of an m6A writer." (PMID 32634481, 2020). "By adoptively transferring WT Treg cells into mice with Mettl14-deficient T cells, we were able to suppress the colitis development." (PMID 32634481, 2020). "The Mettl14-deficient Treg cells were unable to suppress naïve T cell–induced inflammation in a T cell adoptive transfer model of colitis." (PMID 32634481, 2020). "When we transferred Mettl14-deficient Treg cells with the WT naïve T cells into the Rag1–/– mice, the Mettl14-deficient Treg cells were unable to suppress naïve T cell–induced colonic inflammation." (PMID 32634481, 2020). "Similarly, METTL14 deficiency leads to stem cell apoptosis in the mouse colon, resulting in mucosal barrier dysfunction and severe colitis." (PMID 39706833, 2024). "METTL14 deficiency in T cells not only induces colitis but also leads to a decrease in Bacteroidales families S24-7 and Lachnospiraceae, alongside an increase in Bacteroidaceae, Helicobacteraceae, Deferribacteraceae, and Enterobacteraceae when compared to control mice." (PMID 38830900, 2024). "One recent study uncovered that T cell-specific deficiency of METTL14, one of the methyltransferases of m6A, induces spontaneous colitis in mice through inhibiting RORγt expression in Treg cells and promoting the differentiation of naive T cells into Treg cells." (PMID 36792629, 2023). "A recent study finds that METTL14 deficiency in T cells promotes spontaneous colitis in mice." (PMID 34422815, 2021).